MME (membrane metalloendopeptidase)
Diseases named in the same sentence as MME in open-access papers (continued):
Sharing a sentence is not in itself a finding about the gene and the disease.
cardiovascular diseases (3 papers, 2016 to 2024). "Neprilysin [Membrane metallo-endopeptidase (MME) or common acute lymphoblastic leukemia antigen (CALLA) or CD10], a predominantly membrane-bound zinc-dependent metalloproteinase, has been associated with cardiovascular disease and cancer." (PMID 34876625, 2021).
neurodegenerative disease (2 papers, 2018 to 2025). A disorder of the central nervous system characterized by gradual and progressive loss of neural tissue and neurologic function. "Twenty-seven of these associations are known disease loci reported in GWAS, including APOE, MME, CD2AP, CD33 and IL34 for AD, and CD40, CD58, EVI5, IL7R and STAT3 for MS, and 23 associations represent previously unreported genetic associations with neurodegenerative diseases." (PMID 40037332, 2025).
MME also shares sentences with these, for which no sentence is quoted: follicular lymphoma (65 papers); B-cell lymphoma (57); diffuse large B-cell lymphoma (51); Burkitt lymphoma (32); mantle cell lymphoma (32); endometriosis (30); clear cell renal cell carcinoma (24); MALT lymphoma (24); chronic lymphocytic leukemia (20); infection (17); gastric cancer (15); ovarian carcinoma (14); pancreatic cancer (14); sarcoma (14); adenosarcoma (13); acute myeloid leukemia (12); clear cell carcinoma (12); endometrial stromal tumor (12); endometrial stromal sarcoma (11); marginal zone lymphoma (11); bladder cancer (10); leiomyosarcoma (10); systemic lupus erythematosus (10); renal carcinoma (9); cyst (8); hairy cell leukemia (8); T-cell lymphoma (8); urothelial carcinoma (8); adenoma (7); kidney cancer (7).
A further 310 diseases each share a sentence with MME in 7 papers or fewer.